GUSBP9 (GUSB pseudogene 9)
Gene: Transcribed unprocessed pseudogene on chromosome 5 (71,197,646 to 71,208,130, reverse strand). Ensembl gene ENSG00000215630.
Diseases named in the same sentence as GUSBP9 in open-access papers:
GUSBP9 is named in the same sentence as 1 disease in open-access papers, as found by Europe PMC text mining. Sharing a sentence is not in itself a finding about the gene and the disease.
GUSBP9 shares sentences with these, for which no sentence is quoted: tumor (1 paper).